RNF20 (ring finger protein 20)
Diseases named in the same sentence as RNF20 in open-access papers (continued):
Sharing a sentence is not in itself a finding about the gene and the disease.
colitis (4 papers, 2020 to 2025). Inflammation of the colon. "In previous work, genetic loss of function of Rnf20 was shown to predispose mice to acute and chronic colon inflammation, as well as inflammation-associated colorectal cancer." (PMID 40436847, 2025). "Several of these common RNF20/RNF40/VDR targets were shown to be downregulated in experimental colitis, such as Muc2." (PMID 34088983, 2021). "In addition, the expression of RNF20 and RNF40 was down-regulated in the colonic epithelium and in the stroma of UC and colitis-associated colorectal cancer (CAC) patients." (PMID 34956195, 2021). "Apart from the reduced expression of RNF20 in the colon samples from UC patients, homozygous RNF20-knockout mice die due to embryonic lethality, and heterozygous mice are susceptible to DSS-induced colitis with increased intestinal permeability, suggesting the anti-inflammatory role of RNF20." (PMID 32848509, 2020). "Finally, we sought to determine whether gene expression patterns altered following Rnf20 and Rnf40 deletion in IECs may be relevant for murine models for colitis and human IBD." (PMID 34088983, 2021). "In contrast, mice heterozygous for Rnf20 or Rnf40 deletion did not develop spontaneous inflammation and did not display increased sensitivity to DSS-mediated colitis." (PMID 34088983, 2021).
breast tumours (3 papers, 2016 to 2020). "We used a proteogenomic dataset that contains 105 breast tumor samples to determine the clinical relevance of RNF20 by Kaplan-Meier analyses." (PMID 33364200, 2020).
Hyperinsulinemia (3 papers, 2021 to 2025). An increased concentration of insulin in the blood. "Here, we report that the adipocyte-specific knockout of Rnf20 (ASKO) in mice led to progressive fat loss, organomegaly and hyperinsulinemia." (PMID 32797353, 2021).
inflammatory bowel disease (3 papers, 2021 to 2025). A spectrum of small and large bowel inflammatory diseases of unknown etiology. "In intestinal inflammation of inflammatory bowel disease (IBD) patients and mouse models, the loss of H2Bub1 following intestinal Rnf20 or Rnf40 deletion resulted in decreased H3K4me3 occupancy in the transcribed region of various IBD‐associated genes." (PMID 40522008, 2025). "RNF20, encoding the E3 ubiquitin-protein ligase BRE1A, thereby mediates monoubiquitination of histone H2B at lysine 120 and has been shown to play a background-dependent role in the development of inflammatory bowel disease." (PMID 38685026, 2024).
lung carcinoma (3 papers, 2020 to 2025). "To determine the molecular mechanisms leading to spontaneous AD and SCLC formation caused by Rnf20 haploinsufficiency, we first analyzed RNF20 expression in mouse and human lung epithelial and lung cancer cell lines." (PMID 40436847, 2025). "The RNF20 gene encodes an E3 ubiquitin ligase with tumor suppressor function, and it is frequently mutated, particularly in lung cancer." (PMID 32887687, 2020). "Our experiments demonstrated that HIF1α-mediated reprogramming plays a major role in mediating the phenotype elicited upon RNF20 loss, therefore, we next correlated RNF20 levels with the expression of HIF1α and HIF1α-dependent metabolic enzymes in lung cancer patients." (PMID 40436847, 2025). "Interestingly, Wang and colleagues previously reported that loss of H2Bub1 by RNF20 KD results in increased ferroptosis in lung cancer cells by downregulating SLC7A11." (PMID 40597205, 2025). "Next, we investigated the impact of Rnf20 loss on lung cancer development and progression." (PMID 40436847, 2025). "Here we show that an RNF20-HIF1α axis links the DNA damage response and metabolic reprogramming in lung cancer." (PMID 40436847, 2025). "Importantly, decreased RNF20 levels correlate with increased expression of HIF1α and its target genes, suggesting HIF1α inhibition as a promising therapeutic approach for lung cancer patients with reduced RNF20 activity." (PMID 40436847, 2025). "In contrast to RNF20 loss, which markedly promoted cell growth and migration, RNF40 depletion had minimal impact, suggesting distinct roles for these proteins in lung epithelial and lung cancer cells." (PMID 40436847, 2025). "We detected profound DNA damage and greatly increased incidence of lung tumors with characteristics of lung AD and SCLC in Rnf20 haploinsufficient mice, suggesting that non-functional DNA damage repair due to RNF20 loss might be an important factor in the development of lung cancer." (PMID 40436847, 2025). "Notably, RNF40 depletion had minimal impact on the cell growth and migration of lung epithelial cells, suggesting that RNF20 and RNF40 have distinct, independent roles in lung cancer development and progression." (PMID 40436847, 2025).
prostate carcinoma (3 papers, 2018 to 2025). A carcinoma that arises from epithelial cells of the prostate gland. "Numerous studies have implicated RNF20 in oncogenesis and it was found to be somatically mutated or deleted in various cancers including breast, colon, lung, and prostate cancer." (PMID 29934362, 2018). "Variations in RNF20 expression and its interaction with AR play a complex role in prostate cancer progression, offering potential targets for therapeutic intervention." (PMID 40356745, 2025). "The Oncomine database reveals that metastatic prostate cancer cells have decreased the levels of RNF20." (PMID 29934362, 2018). "RNF20 is somatically altered in breast, lung, prostate cancer, clear cell renal cell carcinoma (ccRCC), and mixed lineage leukemia, and its reduced expression is a key factor in initiating genome instability; and it also functions as one of the significant driving factors of oncogenesis." (PMID 29934362, 2018). "In addition to association with ERα and regulation of ER target genes, RNF20 and RNF40 have been shown to physically associate with the AR, with the H2Bub1/RNF20/RNF40 axis implicated in AR-associated gene transcription and affecting the growth of prostate cancer cells." (PMID 33233707, 2020). "Histone ubiquitination, specifically at H2BK120 regulated by RNF20 and RNF40, plays a crucial role in the transcriptional regulation of AR target genes in prostate cancer." (PMID 40356745, 2025). "For example, siRNA (short interfering RNA) down-regulation of RNF20 and RNF40 has been reported to inhibit proliferation of prostate cancer cells." (PMID 33233707, 2020).
viral infection (3 papers, 2013 to 2026). "Transcriptome sequencing analysis revealed that RNA viral infection of DF-1 cells significantly upregulated the expression of chicken RNF20." (PMID 39998124, 2025). "Upon viral infection, RNF20 translocates from the nucleus to the cytoplasm, where it differentially regulates MDA5." (PMID 39998124, 2025). "This suggests that RNF20 dually regulates MDA5-mediated innate immune responses depending on its localization and that viral infection can trigger the nucleocytoplasmic translocation of RNF20." (PMID 39998124, 2025). "In summary, our study found that viral infection triggers RNF20 to dually regulate MDA5-mediated innate immune responses, thereby maintaining innate immune homeostasis." (PMID 39998124, 2025). "Viral infection triggers a switch in the regulatory function of RNF20 through nucleoplasmic translocation." (PMID 39998124, 2025). "This implies that viral infection induces the nucleoplasmic translocation of RNF20, which might negatively regulate the innate immune response." (PMID 39998124, 2025). "Previous studies have demonstrated that monoubiquitination of histone H2B at lysine 120, catalyzed by human RNF20, is essential for the activation of intracellular interferon-stimulated gene (ISG) expression in response to viral infection." (PMID 39998124, 2025). "To demonstrate that viral infection triggers RNF20 to exit the nucleus and target MDA5, thereby modulating the innate immune response, we co-transfected RNF20 with MDA5 into DF-1 cells." (PMID 39998124, 2025). "Here, we uncover that the E3 ubiquitin ligase RNF20 exerts dual regulatory roles in RLR signaling by modulating the expression and promoting the degradation of RIG-I and MDA5 in a nucleocytoplasmic translocation-dependent manner during viral infection." (PMID 41712649, 2026).
colon cancer (2 papers, 2017 to 2021). "RNF20 heterozygous null mice are prone to inflammation-mediated colon cancer." (PMID 29138263, 2017).
congenital heart disease (2 papers, 2021 to 2025). A heart disease that is present at birth. "Importantly, RNF20 expression is significantly reduced in cardiac endothelial cells from congenital heart disease patients showing a positive correlation with oxygen saturation and a negative correlation with key components and downstream effectors of TGF-β signaling." (PMID 41145490, 2025).
liver cancer (2 papers, 2025). An epithelial or non-epithelial malignant neoplasm that arises from the liver. "Overexpression of ring finger protein 20 (RNF20) in liver cancer is positively associated with postoperative survival rates and inhibits cell proliferation and metastasis by promoting NLRP3 ubiquitination." (PMID 41291696, 2025).
osteosarcoma (2 papers, 2013 to 2025). A usually aggressive malignant bone-forming mesenchymal neoplasm, predominantly affecting adolescents and young adults. "To investigate this, we generated two shRNAs; one corresponding to UTR (shRNF20 #1) and one gene-specific (shRNF20 #2) and examined replication stress markers in the control and RNF20-depleted U2OS human osteosarcoma cells." (PMID 40495033, 2025).
acute myeloid leukemia (1 paper, 2020). Acute myeloid leukemia (AML) is a group of neoplasms arising from precursor cells committed to the myeloid cell-line differentiation. "RNF20 has also been identified as necessary for proliferation, both in vitro in mixed-lineage leukemia (MLL)-rearranged human acute myeloid leukemia (AML) cell lines and in vivo, being important for disease progression in a genetically engineered mouse model of AML." (PMID 33233707, 2020).
cervical cancer (1 paper, 2025). A primary or metastatic malignant neoplasm involving the cervix. "We showed that high RNF20 and RNF40 levels correlate with cervical cancer cell aggressiveness and poor patient prognosis." (PMID 40597205, 2025). "Despite its well-established significance in various malignant diseases, the role of RNF20 and RNF40 in cervical cancer remains poorly understood." (PMID 40597205, 2025). "Together, our results indicate that interfering with RNF20 and RNF40 driven H2Bub1 and the peroxisome transcriptional program could provide a novel target for a therapeutic approach against aggressive cervical cancer." (PMID 40597205, 2025).
cholangiocarcinoma (1 paper, 2019). A carcinoma that arises from the intrahepatic biliary tree (intrahepatic cholangiocarcinoma) or from the junction, or adjacent to the junction, of the right and left hepatic ducts (hilar cholangiocarcinoma). "In cholangiocarcinoma, MEG3 level was found to have been significantly decreased in cholangiocarcinoma tissues and cells as compared to that in nontumor controls and it suppressed cell proliferation and invasion via regulating Bmi1/RNF20." (PMID 31729423, 2019).
Crohn disease (1 paper, 2021). A gastrointestinal disorder characterized by chronic inflammation involving all layers of the intestinal wall, noncaseating granulomas affecting the intestinal wall and regional lymph nodes, and transmural fibrosis. "Finally, these effects were confirmed in a subgroup of Crohn’s disease patients which displayed epigenetic and expression changes in RNF20/40-dependent gene signatures." (PMID 34088983, 2021).
female infertility (1 paper, 2024). Diminished or absent ability of a female to achieve conception. "Our findings regarding RNF20 localization and female infertility in Rnf20‐knockout mice led us to investigate the function of RNF20 in oocyte maturation." (PMID 38240347, 2024).
glioma (1 paper, 2019). A benign or malignant brain and spinal cord tumor that arises from glial cells (astrocytes, oligodendrocytes, ependymal cells). "In glioma in vitro models, IPA induces EGFR ubiquitination through the upregulation of c-Cbl, an E3 ligase belonging to RING—domain ligase family such as SCFFBXW7 and RNF20." (PMID 31569395, 2019).
immune deficiency (1 paper, 2025). "Overexpression of RNF20 markedly suppresses the expression of chicken innate immunity-related genes, while RNF20 knockout leads to immune deficiency both in vivo and in vitro." (PMID 39998124, 2025). "Surprisingly, both RNF20 knockout cells and chickens exhibited immunodeficiency." (PMID 39998124, 2025). "However, RNF20 knockout results in immunodeficiency both in vitro and in vivo." (PMID 39998124, 2025).
Infertility (1 paper, 2024). "Next, we found that oocyte‐specific knockout of Rnf20 results in complete infertility of female mice by causing severe abnormal spindle and chromosome misalignment due to defective bipolar organization of spindles." (PMID 38240347, 2024).
Insulin resistance (1 paper, 2025). Increased resistance towards insulin, that is, diminished effectiveness of insulin in reducing blood glucose levels. "Specifically, we observed that complete ablation of the Rnf20 gene in adipocytes, which encodes the E3 ligases responsible for H2B monoubiquitination, led to hyperinsulinaemia and adipose tissue‐specific insulin resistance in mice." (PMID 40522008, 2025). "Further molecular analysis demonstrated that the loss of RNF20 reduced H3K4me3 modifications at the Slc2a4 gene locus, thereby decreasing its expression and ultimately contributing to the development of insulin resistance." (PMID 40522008, 2025). "However, whether overexpression of the Slc2a4 gene in RNF20 knockdown cells could alleviate insulin resistance remains to be investigated, which would better elucidate the role of RNF20 in insulin signalling via Slc2a4 regulation." (PMID 40522008, 2025). "Further research is needed to determine whether RNF20 indirectly regulates systemic insulin homoeostasis through inter‐organ signalling mechanisms, providing potential new therapeutic targets for treating insulin resistance‐related metabolic disorders." (PMID 40522008, 2025). "Mechanistically, Rnf20 knockdown in adipocytes reduced H3K4me3 occupancy at the Slc2a4 gene locus, inhibiting GLUT4 expression and inducing adipose‐specific insulin resistance." (PMID 40522008, 2025).
Lewis lung carcinoma (1 paper, 2025). "Consistent findings were observed with siRNA-mediated silencing of RNF20 in the human small-cell lung cancer cell line H82, as well as with the ablation of a single Rnf20 allele in murine Lewis lung carcinoma (LLC1) cells." (PMID 40436847, 2025). "Lower levels of RNF20 were observed in A549, A427 and H322 adenocarcinoma as well as human H82 and H69 small-cell lung cancer cells compared to normal human bronchial epithelium (BEAS-2B) cells and in mouse Lewis lung carcinoma (LLC1) cells compared to mouse lung epithelial (MLE12) cells." (PMID 40436847, 2025).
liver fibrosis (1 paper, 2021). "Besides, ring finger protein 20 (RNF20), also known as E3 ubiquitin-protein ligase BRE1A, has been demonstrated to inactivate IL-6, TNF-α, VEGFA, α-SMA as well as collagen I and alleviate liver fibrosis via ubiquitination of H2BK120 (H2BK120ub) in vitro and in vivo." (PMID 34887768, 2021).
male infertility (1 paper, 2023). The inability of the male to effect fertilization of an ovum after a specified period of unprotected intercourse. "In the present study, we created a Rnf20 conditional knockout in the Sertoli cells and find that deficiency of Rnf20 leads to male infertility owing to spermatogenic failure in mice, recapitulating pathological features of the SCOS in humans." (PMID 37024990, 2023). "The Sertoli cells-specific knockout of Rnf20 causes male infertility through regulation of the cascade RNF20-H2BK120ub-CLDN11 during spermatogenesis in the mouse testis." (PMID 37024990, 2023). "Together, these data indicated that the Sertoli cells-specific knockout of Rnf20 in mice caused male infertility owing to spermatogenic failure, recapitulating pathological features of the SCOS in humans." (PMID 37024990, 2023). "We uncover Rnf20 as a new causative gene for spermatogenic failure and male infertility." (PMID 37024990, 2023). "The Sertoli cells-specific knockout of Rnf20 causes male infertility." (PMID 37024990, 2023). "Knockout of Rnf20 disrupts the prime factor in the regulatory cascade RNF20-H2BK120ub-CLDN11 during spermatogenesis and eventually causes male infertility." (PMID 37024990, 2023). "Our study provides a mouse model of the Rnf20 knockout, that recapitulates the Sertoli cell-only syndrome in humans, a serious condition for male infertility." (PMID 37024990, 2023). "The pathogenetic mechanism is involved in epigenetic regulation of the RNF20 in male infertility." (PMID 37024990, 2023).
neuroblastoma (1 paper, 2020). Neuroblastoma (NB) is the most common solid, extracranial childhood tumor. "For this purpose, we analyzed the ability of ectopic Egr2 to induce the expression of its target genes in Neuro2a neuroblastoma cells with varying levels of Rnf40/Rnf20 E3 ligase activity." (PMID 32672815, 2020).
ovarian tumors (1 paper, 2022). "The loss of RNF20 (Ring Finger Protein 20) and H2Bub1 (H2B monoubiquitination) to the progression of ovarian tumors by chromatin remodelling has been reported by a very recent study." (PMID 36092905, 2022).
renal carcinoma (1 paper, 2025). A carcinoma arising from the epithelium of the renal parenchyma or the renal pelvis. "Altered/loss of expression of RNF20/RNF40 has been observed in various cancer cells, including breast, lung, prostate and renal cancers, implying the role of RNF20/40 in tumor suppression." (PMID 40495033, 2025).
renal cell cancer (1 paper, 2019). "Furthermore, overexpression of RNF20 in renal cell cancer cell lines led to a decrease in proliferation, while suppression of RNF20 led to increased proliferation." (PMID 30669413, 2019).
Sertoli Cell-Only Syndrome (1 paper, 2023). A type of male infertility in which no germ cells are visible in any of the biopsied SEMINIFEROUS TUBULES (type I) or in which germ cells are present in a minority of tubules (type II). "This study describes a Rnf20 knockout mouse model that recapitulates the Sertoli cell-only syndrome in humans and demonstrates that RNF20 is required for male fertility through regulation of H2B ubiquitination in the Sertoli cells." (PMID 37024990, 2023).
small cell lung carcinoma (1 paper, 2025). Small cell lung cancer (SCLC) is a highly aggressive malignant neoplasm, accounting for 10-15% of lung cancer cases, characterized byrapid growth, and early metastasis. "Here, we show that Rnf20 haploinsufficiency leads to the spontaneous formation of lung tumors, showing similar morphology and histopathology to human adenocarcinoma and small cell lung carcinoma (SCLC)." (PMID 40436847, 2025).
squamous cell carcinoma (1 paper, 2025). A carcinoma arising from squamous epithelial cells. "By contrast, we did not observe changes in RNF20 mRNA levels or association with patient survival in squamous cell carcinoma patients." (PMID 40436847, 2025).
Tetralogy of Fallot (1 paper, 2025). A congenital cardiac malformation comprising pulmonary stenosis, overriding aorta, ventricular septum defect, and right ventricular hypertrophy. "In this study, we found a significant reduction in RNF20 levels in cardiac endothelial cells from patients with Tetralogy of Fallot (TOF), which positively correlates with oxygen saturation and inversely correlates with the expression of key components and downstream effectors of TGF-β signaling." (PMID 41145490, 2025).
uterine corpus endometrial carcinoma (1 paper, 2023). A endometrial carcinoma (disease) that involves the body of uterus. "Notably, the N-terminal segment of RNF20 that interacts with hRad51 harbors two groups of clustered mutations in uterine corpus endometrial carcinoma patients." (PMID 37230987, 2023).